CH25H (cholesterol 25-hydroxylase)
Diseases named in the same sentence as CH25H in open-access papers (continued):
Sharing a sentence is not in itself a finding about the gene and the disease.
glioblastoma (1 paper, 2023). The most malignant astrocytic tumor (WHO grade IV). "Specifically, the transcription and translation of CH25H have been found to increase in response to TNFα and IL1β in glioblastoma cell lines." (PMID 37208656, 2023).
Granuloma (1 paper, 2014). A compact, organized collection of mature mononuclear phagocytes, which may be but is not necessarily accompanied by accessory features such as necrosis. "Nevertheless, C. burnetii-induced granulomas were not only characterized by anti-inflammatory program; indeed, C. burnetii did induce several genes related to inflammation such as TNFSF13, CH25H, and IRF7 genes." (PMID 25566510, 2014).
haemorrhages (1 paper, 2025). "Overall, our data indicate that CH25H upregulation is part of an antiviral response in SARS-CoV-2-associated haemorrhages in both developing zebrafish and human brains, and that CH25H upregulation can be directly induced by antiviral signalling in neuroendothelial and glial cells." (PMID 40406995, 2025).
Hepatitis (1 paper, 2016). Inflammation of the liver. "CH25H is an interferon-stimulated gene, and its expression is upregulated during infection with hepatitis C and influenza viruses." (PMID 27999160, 2016).
Listeria monocytogenes infection (1 paper, 2023). "Previous work has demonstrated that Ch25h-deficient macrophages overproduce IL-1β and have deregulated caspase-1-activating inflammasome activity in response to Listeria monocytogenes infection or LPS stimulation." (PMID 36831236, 2023).
liver cancer (1 paper, 2020). An epithelial or non-epithelial malignant neoplasm that arises from the liver. "At the cellular level, YBX3 and CH25H were highly expressed in liver cancer cell lines, and ABCA6, PLIN5, AMACR, AKR1D1, CYP27A1, CYP46A1 were highly expressed in liver cancer cell lines in CCLE." (PMID 32627826, 2020).
metastatic tumors (1 paper, 2022). "Notably, low expression of CH25H in leukocytes is an obvious molecular characteristic of metastatic tumors which results in poor prognosis." (PMID 36564433, 2022).
muscular atrophy (1 paper, 2025). The loss of muscle tissue due to inactivity or disease. "Other relevant genes, such as TLL2, CH25H, and ST13, affect muscular atrophy and adipocyte differentiation." (PMID 41373569, 2025).
ovarian carcinoma (1 paper, 2020). A malignant neoplasm originating from the surface ovarian epithelium. "Our study used the Kaplan-Meier method and univariate Cox regression analysis to show that CH25H, HSPB7, and PPM2C correlated with ovarian cancer patients that had the worst prognoses." (PMID 33381581, 2020).
pancreatic cancer (1 paper, 2023). "For example, in pancreatic cancer, the loss of CH25H expression is associated with the downregulation of MHC-I and decreased CD8+ T-cell tumor infiltration." (PMID 37981011, 2023).
Parkinson disease (1 paper, 2015). A progressive degenerative disorder of the central nervous system characterized by loss of dopamine producing neurons in the substantia nigra and the presence of Lewy bodies in the substantia nigra and locus coeruleus. "In addition, ELD-T genes also included some oxidation-reduction genes, such as WW domain containing oxidoreductase, Parkinson disease (autosomal recessive, juvenile) 2, parkin, oxoglutarate (alpha-ketoglutarate) dehydrogenase (lipoamide) and cholesterol 25-hydroxylase." (PMID 26346824, 2015).
primary progressive MS (1 paper, 2019). "Genetic analysis of MS patients further revealed a potential association between genetic variants of cholesterol 25-hydroxylase (Ch25h) and primary progressive MS patients, supporting a role for Ch25h and related-oxysterols in CNS autoimmunity." (PMID 31547302, 2019).
promyelocytic leukemia (1 paper, 2024). "For example, 50 μM of 25HC induced IL-8 secretion in U937 human promyelocytic leukemia of neuronal cells; however, 0.1 μM of 25HC decreased LPS-induced IL-1β mRNA and protein and inflammasome activation in cholesterol-25-hydroxylase-defficient bone-marrow-derived monocytes." (PMID 39595101, 2024).
Sepsis (1 paper, 2023). Sepsis is defined as life-threatening organ dysfunction caused by a dysregulated host response to infection. "Generation of endothelial specific Ch25h-null mice will be required to resolve this question, and future investigations with extrapulmonary/vascular models of acute lung injury (e.g., sepsis) may also be revealing." (PMID 36821369, 2023).
Stroke (1 paper, 2023). Sudden impairment of blood flow to a part of the brain due to occlusion or rupture of an artery to the brain. "We identified CH25H+ microglia as a neuroprotective subpopulation, and found Ch25h deficiency in microglia exacerbated ischemic brain injury and neuroinflammation after stroke." (PMID 37183260, 2023). "Collectively, our findings identified MKI67+ microglia as the proliferative, CH25H+ as the neuroprotective, while OASL+ as the proinflammatory microglia subcluster which was associated with ischemic brain injury 3 days after stroke." (PMID 37183260, 2023). "The blood brain barrier (BBB) disruption was exacerbated in Ch25h−/− mice compared to Ch25h+/− mice after stroke." (PMID 37183260, 2023). "We found prolonged latency to fall and increased foot fault percentage in Ch25h−/− mice compared to Ch25h+/− mice 5 days after stroke." (PMID 37183260, 2023). "Ch25h−/− mice were used to investigate the role of specific microglia subcluster on post-stroke infarct volume and neuroinflammation." (PMID 37183260, 2023). "Thus, Ch25h could be an intriguing target for modulating the protective microglia subcluster for stroke therapy." (PMID 37183260, 2023). "The cholesterol 25-hydroxylase (Ch25h) was specifically expressed in MG6, and CH25H+ IBA1+ cells could be found in the ischemic penumbra starting from 1 day and gradually increased up to 7 days after stroke." (PMID 37183260, 2023).
tauopathy (1 paper, 2025). Neurodegenerative disorders involving deposition of abnormal tau protein isoforms (tau proteins) in neurons and glial cells in the brain. "In response to inflammation, CH25H is upregulated and 25HC levels increase within the brain, as observed in murine models involving lipopolysaccharide challenge and tauopathy neurodegeneration." (PMID 40406995, 2025).
tuberculosis (1 paper, 2025). A chronic, recurrent infection caused by the bacterium Mycobacterium tuberculosis. "Supporting this idea, CH25H expression has been reported around human tuberculosis granulomas." (PMID 40766699, 2025).
infection (36 papers, 2011 to 2026). The state of being infected such as from the introduction of a foreign agent such as serum, vaccine, antigenic substance or organism. "To expand these results, we investigated if there was an age-associated alteration in Ch25h expression in young and aged lungs at baseline and in response to infection." (PMID 39717487, 2024). "During infection, mice with Ch25h overexpression were highly susceptible to Listeria monocytogenes, Mycobacterium tuberculosis, and influenza." (PMID 39717487, 2024). "Using in vitro and in vivo murine models of S. pneumoniae, we observed an age-associated increase in Ch25h expression in aged AM during infection." (PMID 39717487, 2024). "They found that Ch25h−/− mice were more susceptible to infection by CDC injected in skin than WT animals, but preinjection of 25-HC reduced subsequent tissue damage." (PMID 34953867, 2022). "(i) Infection and inflammation, notably in macrophages associated with the vasculature, induce the expression of CH25H." (PMID 24656052, 2014). "Using a severe acute respiratory syndrome coronavirus 2 (SARS-CoV-2) spike protein-induced zebrafish ICH model and foetal human SARS-CoV-2-associated cortical tissue containing microbleeds, we identified upregulation of CH25H in infection-associated cerebral haemorrhage." (PMID 40406995, 2025). "Following lymphocytic choriomeningitis virus (LCMV) challenge, Ch25h undergoes significant upregulation not only in LN vasculature but also within interfollicular and outer T-zone stromal cells at 24-h post-infection." (PMID 40358827, 2025). "The results showed that CH25H mRNA was dramatically upregulated starting at 12 hours post-infection (hpi), peaked at 24 hpi, and decreased at 36 hpi, while NDV NP mRNA levels were significantly increased with time." (PMID 40261014, 2025). "The antiviral enzyme cholesterol 25-hydroxylase (CH25H) and its metabolite 25-hydroxycholesterol (25HC), which modulates cholesterol metabolism during infection, have been associated with vascular pathology." (PMID 40406995, 2025). "We next evaluated the impact of Ch25h knockdown on inflammatory cytokines, such as Serpine-1 and Tnf, and observed a significant decrease in expression in aged macrophages during infection." (PMID 39717487, 2024). "Compared to young, a significant increase in Ch25h expression was observed in aged macrophages at baseline, which continued to increase in response to infection." (PMID 39717487, 2024). "We next evaluated the potential impact of Ch25h siRNA treatment on antibacterial signaling in the lung at 24 h post-infection." (PMID 39717487, 2024). "In this study, the expression of chicken CH25H (chCH25H) was found to be upregulated in ARV-infected cells at the early stage of infection." (PMID 37455710, 2023). "In contrast, there was decreased granulocyte-macrophage colony-stimulating factor (GM-CSF) and macrophage colony-stimulating factor (M-CSF) in Ch25h−/− lung at 24 h post-infection." (PMID 36831236, 2023). "The overexpression of CH25H or the treatment with exogenous 25HC abolishes infection by SARS-CoV, MERS-CoV, or SARS-CoV-2 pseudoviruses in Calu-3 cells." (PMID 38106410, 2023). "LY6E and CH25H (cholesterol 25-hydroxylase) are two ISGs that impair coronavirus initiation of infection by impairing fusion and entry." (PMID 37364688, 2023). "In response to infection, there was a significant, Ch25h-dependent increase in Nlrp3, Pycard, and Casp1 gene expression observed at 24 h post-infection." (PMID 36831236, 2023). "Taken together, these results indicated that ARV infection triggered the induction of CH25H at the early stage of infection." (PMID 37455710, 2023). "Our study was designed to investigate the impact of Ch25h on mediating innate immune responses by macrophages during infection by S. pneumoniae infection." (PMID 36831236, 2023).
infection (continued). "Apart from antiviral mechanisms depending on enzyme activity, CH25H can also inhibit the infection of some viruses via a hydroxylase-independent mechanism." (PMID 37455710, 2023). "To test the consequence of CH25H gene activity in Mo-DC we treated cells with 25-HC during infection." (PMID 34381163, 2021). "We performed a similar experiment in human macrophages and found increased expression of CH25H following infection, in agreement with the published studies using Lm-infected murine macrophages." (PMID 34381163, 2021). "CH25H expression is also induced in response to infection with Zika virus, Singapore grouper iridovirus and red-spotted grouper nervous necrosis virus, and subsequently blocks viral attachment by 25HC." (PMID 32208449, 2020). "We found that CH25H is consistently increased during de novo infection of HUVECs (primary cells) but repressed in latently infected cell lines MC116.219 and iSLK." (PMID 28698273, 2017). "CH25H expression is induced in MHV68 de novo infection of primary macrophages shortly after infection." (PMID 28698273, 2017). "25HC is produced by the enzyme cholesterol 25-hydroxylase (Ch25h) and belongs to a family of bioactive cholesterol derivatives produced by cells in response to fluctuating cholesterol levels and also during infection." (PMID 26812621, 2016). "In the following experiments, infection of Mφ with MCMVdie3 resulted in an equal response of Ch25h activation in comparison with the parental wild-type (WT) virus but with slightly delayed temporal kinetics." (PMID 23273843, 2013). "This may be due to different mechanisms of regulation of CH25H expression after infection with different viruses." (PMID 37455710, 2023). "In summary, we have demonstrated for the first time that ARV infection triggers the induction of the interferon-stimulated protein CH25H at the early stage of infection, and CH25H suppresses ARV replication by its product 25HC, depending on its enzyme activity." (PMID 37455710, 2023). "For SVA, CH25H expression was downregulated during SVA infection and the degradation of CH25H becomes more serious with the prolongation of infection, which maybe a strategy for SVA to antagonize the antiviral effect of CH25H." (PMID 36618383, 2022). "On the other hand, recent studies have identified CH25H as an infection-inducible gene." (PMID 36423680, 2022). "CH25H, the enzyme regulating synthesis of 25HC, can suppress infection with PDCoV." (PMID 36314946, 2022). "This suggests that there may exist antiviral host mechanisms to upregulate CH25H upon de novo infection (3 dpi) and viral miRNAs suppress multiple steps of the mevalonate pathway to suppress this antiviral response." (PMID 28698273, 2017). "Infection and inflammation selectively induce the expression of cholesterol 25-hydroxylase (CH25H)." (PMID 24656052, 2014). "Does infection/inflammation in brain microglia also upregulate CH25H expression?" (PMID 24656052, 2014). "Inaddition, 25HC has been identified as a natural ligand for RORyt.The fact that PPARy deficiency was linked to CH25H overexpression, prompted our initial hypothesis thatT0070907 blocks HIV outgrowth ex vivo and infection invitro and boosts Th17 effector functions via CH25H/25HC-dependentmechanisms." (PMID 33089034, 2020). "On the basis of all these findings, the present study proposed a working model for CH25H-mediated dual regulation of HBV replication and infection." (PMID 35587189, 2022). "These ISGs, such as CH25H, MX, PKR, OAS, and ZAP, have been proven to block virus invasion in different ways to protect cells from infection." (PMID 33628117, 2021). "Unlike Ch25h, Cyp7b1 is widely expressed in fibroblastic reticular cells (FRCs) within the T-cell zone of LNs, showing no significant alterations at 24-h post-infection." (PMID 40358827, 2025).
infection (continued). "The upregulation of CH25H and downregulation of CYP7A1 in the current study suggest that pathogen infection may not only affect the BA metabolism, but also cholesterol metabolism, which needs to be further confirmed." (PMID 39287458, 2024). "For example, after infection with viruses such as ZIKV, VSV and HIV, CH25H expression is significantly upregulated in host cells, whereas after infection with viruses such as PRRSV and HSV, CH25H expression is significantly downregulated." (PMID 37455710, 2023). "Notably, Cyp7b1 does not significantly increase upon infection, suggesting that Ch25h induction in macrophages is rate-limiting for production of chemotactic oxysterols in the lung." (PMID 40766699, 2025). "Interestingly, by 72 h of infection, in the absence of Ch25h, there was a significant increase in Pycard and Casp1 gene expression observed." (PMID 36831236, 2023). "Interestingly, infection of Mo-DC downregulated CH25H expression, suggesting that Type I IFN are not coordinately regulated CH25H as has been reported in other cell types." (PMID 34381163, 2021). "The increase in EBI2’s homing role was not as large as occurring after infection, perhaps due to incomplete CCL21 blocking and lack of Ch25h upregulation." (PMID 39708807, 2025). "A catalytic mutant CH25H, which loses cholesterol 25-hydroxylase activity, failed to inhibit Hantavirus, Avian reovirus, Seneca Valley virus, VSV-SARS-CoV-2 chimeric virus, and Rabies virus (RABV) infection." (PMID 40261014, 2025).
tumor (26 papers, 2014 to 2026). "Previous studies have shown that CH25H (cholesterol 25‐hydroxylase) is associated with extracellular vesicles involved in tumor progression, cholesterol metabolism, and cellular immunity, but its role in T cells has not been clarified." (PMID 40860436, 2025). "All models exhibited consistent findings, demonstrating higher levels of CH25H expression in tumor‐associated MDSCs." (PMID 41020041, 2025). "Given that loss of CH25H is associated with cancer immune evasion, it is plausible that agents preserving the levels of CH25H in DCs would exhibit immunostimulatory and anti-tumor properties." (PMID 36333297, 2022). "Here the authors find that downregulation of cholesterol 25-hydroxylase underlies defective cross presentation of tumour antigens." (PMID 36333297, 2022). "These previous studies suggest that CH25H may also be associated with positive regulation of tumor immunity in LUAD." (PMID 36564433, 2022). "High CH25H expression may cause high infiltration level, i.e. “hot” tumor." (PMID 36564433, 2022). "scRNA-seq identified cancer-associated immune signatures, notably consistent upregulation of THBS1 and CH25H, indicative of systemic imprinting by tumour-derived cues." (PMID 42308424, 2026). "Compared to the Ch25hf/f mice, the subcutaneous tumors in the Ch25hf/fLyz2Cre(±) mice demonstrated a slower growth rate, along with reduced tumor volume and weight following the myeloid‐specific knockdown of CH25H." (PMID 41020041, 2025). "The final results demonstrated that the number of MDSCs was significantly increased in tumor tissues compared to paraneoplastic tissues, with a concurrent upregulation of CH25H expression in MDSCs." (PMID 41020041, 2025). "Data demonstrated that CH25H expression was lower in bone metastatic tissue compared to the 4T1 primary tumor." (PMID 38405101, 2024). "We found that among all the CSCC patients, those with the high expression level of CH25H in tumor tissue had a higher survival probability, indicating that CH25H mRNA expression is positively correlated with the survival probability of CSCC patients." (PMID 38472192, 2024). "Using GEO2R, we analyzed the publicly available RNAseq data set GSE58135 to compare CH25H expression in TNBC tumor tissue and normal adjacent tissue." (PMID 38405101, 2024). "Depletion of CH25H has been shown to promote an increase in neutrophils in tumor‐specific cytotoxic T lymphocytes, weaken antitumor immunity, and stimulate tumor growth." (PMID 39428922, 2024). "Based on relevant literature review, CH25H has been confirmed to be related to tumor immune escape and tumor microenvironment." (PMID 39428922, 2024). "Such oxidization is mediated by the cholesterol 25-hydroxylase, which is upregulated in the irradiated tumor cells during the preparation of tumor cell-derived MPs." (PMID 36658134, 2023). "Given that CH25H is already downregulated in the tumor microenvironment in WT mice, these differences are likely underappreciated." (PMID 36333297, 2022). "We next sought to examine the importance of downregulation of CH25H in DCs for anti-tumor immunity and tumor growth." (PMID 36333297, 2022). "In turn, downregulation of CH25H in the intratumoral DCs leads to augmented lysosomal proteolysis of antigens and results in an impaired antigen cross presentation and accelerated tumor growth." (PMID 36333297, 2022). "Nevertheless, they indicate that downregulation of CH25H in DCs impedes the T cell-based anti-tumor immune responses and stimulates tumor growth." (PMID 36333297, 2022). "Since CH25H restricts the lysosomal degradation of antigens, the net results of the ATF3-CH25H regulatory axis include an acceleration of antigen proteolysis and resulting poor cross-presentation of tumor antigens by the intratumoral DCs." (PMID 36333297, 2022).